ALB (albumin)
Diseases named in the same sentence as ALB in open-access papers (continued):
Sharing a sentence is not in itself a finding about the gene and the disease.
liver cirrhosis (continued). "Moreover, high burden of oxidized albumin is associated with less favorable outcome in patients with liver cirrhosis." (PMID 30930689, 2019). "Subjects with liver cirrhosis had significantly higher malignancy rates than subjects without liver cirrhosis in addition to a significantly higher all-cause mortality rate and lower mean values of hemoglobin concentration, serum albumin, and cholesterol." (PMID 30973940, 2019). "In addition, reduced albumin synthesis may affect calcium transport disorders, and hypocalcemia is associated with a more severe form of decompensated liver cirrhosis." (PMID 38791276, 2024). "In patients with liver cirrhosis, the decrease in serum Na+ caused by water and sodium storage, as well as the inversion of the A/G ratio and the subsequent decrease of plasma colloidal osmotic pressure caused by insufficient synthesis of ALB, are all essential factors in the development of ascites." (PMID 34291096, 2021). "Plasma LCAC levels were positively correlated with liver cirrhosis and total bilirubin, and negatively correlated with albumin." (PMID 40370557, 2025). "Albumin is a well-recognized indicator of nutrition and liver function and one of the most frequent significant prognostic predictors of liver cirrhosis." (PMID 40747208, 2025). "The impact of increased OR for low albumin levels was highest on liver cirrhosis history (3.33, 2.10–5.28)." (PMID 41248155, 2025). "For example, BCAA supplementation has helped maintain serum albumin levels in patients with liver cirrhosis or hepatocellular carcinoma." (PMID 41375751, 2025). "The ALBI score only relied on albumin and bilirubin, directly reflecting the reserve capacity of liver parenchymal cells, while the core driving factor of liver cirrhosis mortality is the failure of liver parenchymal function." (PMID 40936688, 2025). "Additionally, patients with liver cirrhosis are usually placed on a diuretic regimen to offload the fluid buildup/edema in the body, and as such, these means lead to increased loss of both zinc and albumin in the urine, further accentuating the deficiency of zinc." (PMID 40400889, 2025). "One study compared two groups of patients with liver cirrhosis: one group receiving diuretic and the other group receiving diuretics as well as albumin." (PMID 38551716, 2024). "Exclusions were made for 28 participants with outlier values in liver function parameters (AST above 63, ALT above 62, ALP above 189, total bilirubin above 1.7, and albumin below 2.8), four with hepatocellular carcinoma, and six with liver cirrhosis." (PMID 39114318, 2024). "In the cohort excluding patients with liver cirrhosis CE levels correlated with bilirubin (r = −0.428, p < 0.001), albumin (r = 0.233, p = 0.014), AST (r = −0.204, p = 0.034) and gamma GT (r = 0.210, p = 0.039)." (PMID 39311203, 2024). "These variables included liver cirrhosis (P = 0.036), ALB (P = 0.049), Ki-67 (P = 0.054), and Child-Pugh score (P = 0.084)." (PMID 38720338, 2024). "A significant correlation was found between microinvasion and liver cirrhosis (P = 0.036), serum albumin level (P = 0.049)." (PMID 38720338, 2024). "We observed that lower-albumin groups had more malignancy, chronic renal disease, and liver cirrhosis." (PMID 39459557, 2024). "Secondly, patients with liver cirrhosis demonstrate post-translational alterations to albumin that limit its amount and function." (PMID 38813321, 2024). "Fifth, we conducted correlation analyses between age, liver cirrhosis, and serum albumin levels prior to proceeding with the multivariate analysis model and found significant associations." (PMID 38639116, 2024). "A panel of hepatologists, advanced liver nurses and one haematologist, were invited to a roundtable meeting to discuss the use of long‐term albumin infusions for liver cirrhosis." (PMID 39301299, 2024).
liver cirrhosis (continued). "The five included studies reported demographic data of all patients or patients with liver cirrhosis, including age, sex, hemoglobin, total bilirubin (TB), albumin, and alpha-fetoprotein (AFP), and they were extremely comparable." (PMID 39398946, 2024). "Recently, albumin infusion has been proposed to treat various complications of liver cirrhosis because of its oncotic and anti-inflammatory properties." (PMID 38999366, 2024). "Diagnosis of liver cirrhosis was based on clinical examination, serum albumin level, and prothrombin time followed by characteristic findings on ultrasound." (PMID 39040780, 2024). "BCAAs not only serve as an energy substrate in patients with liver cirrhosis but also improve liver regeneration, immune function, albumin production, ammonia metabolism, and insulin sensitivity." (PMID 39068612, 2024). "The incidence of liver cirrhosis was 75 (63.56%), and 54 (46.15%) were in albumin bilirubin (ALBI) grade 1, while 63 (53.85%) were in ALBI grade 2." (PMID 38646432, 2024). "Malignancy and liver cirrhosis were more common in the lower albumin groups, while the cardiac disease was more common in the higher albumin groups." (PMID 39459557, 2024). "Longer-term supplementation with BCAA raises plasma albumin, benefits quality of life issues, and, finally, improves survival in liver cirrhosis." (PMID 39064737, 2024). "Changes in albumin concentration are closely related to the progression of liver diseases and the occurrence of various events, including gastroesophageal varices, liver cirrhosis, and encephalopathy as a consequence of fibrosis." (PMID 38791276, 2024). "It has been demonstrated that in patients with liver cirrhosis, albumin undergoes both several reversible and irreversible posttranscriptional changes that alter its properties." (PMID 37569584, 2023). "Chicory extract administered to rats with thioacetamide-induced liver cirrhosis was able to normalize serum liver enzyme activity, albumin, and bilirubin levels." (PMID 37895942, 2023). "In females with liver cirrhosis SM 36:2;O2 and 38:2;O2 positively correlated with albumin levels before DAA therapy." (PMID 37176109, 2023). "The ability to synthesize albumin can reportedly be reduced by 60–80% in patients with advanced liver cirrhosis." (PMID 37726716, 2023). "In patients with liver cirrhosis, in addition to being used as a monitoring index of liver function, ALB level is also negatively correlated with the degree of esophageal varices; this aspect can be used as a good predictor of esophageal varices bleeding." (PMID 37715244, 2023). "In patients with liver cirrhosis, scar tissue compresses blood vessels inside the liver and leads to increased portal vein pressure and decreased albumin synthesis owing to impaired liver function, which results in fluid accumulation, such as ascites." (PMID 37345189, 2023). "Compared with the CON group, TBil, ALT, AST and BNP were significantly increased, and ALB was decreased in the liver cirrhosis groups, especially in the Child-Pugh C group (P < 0.05)." (PMID 36970359, 2023). "In females with liver cirrhosis, the three SM species found to be related to albumin also correlated with HDL." (PMID 37176109, 2023). "There are reduced albumin synthesis and aberrant structure and function of albumin in the serum of liver cirrhosis patients." (PMID 38264288, 2023). "The univariate analyses showed that baseline age, AMA titer, platelet count, Bil (T) and albumin levels, and UDCA response were associated with liver cirrhosis development." (PMID 35663951, 2022). "Her ascetic fluid analysis was transudative with a serum ascites albumin gradient >1.1, and the abdomen and pelvis ultrasonography reported liver cirrhosis with splenomegaly with perisplenic varices." (PMID 36523670, 2022). "The use of human albumin (HA) in the management of liver cirrhosis with hyponatremia remains controversial among the current practice guidelines." (PMID 36233795, 2022).
liver cirrhosis (continued). "When albumin is reduced or varicose veins are serious in liver cirrhosis patients, more attention should be given to the occurrence and severity of PHG." (PMID 36241992, 2022). "GA levels should be interpreted cautiously in disorders with abnormal albumin turnover, such as nephrotic syndrome, liver cirrhosis etc." (PMID 36251516, 2022). "The severity of liver cirrhosis is a prognostic indicator of liver fibrosis, and a decrease in ALB levels indicates liver function damage." (PMID 36059967, 2022). "Second, the level and function of albumin are affected by many liver-related diseases, such as liver cirrhosis, and patients with liver cirrhosis present post-translational modifications to albumin that compromise its level and function." (PMID 36145159, 2022). "We found that DKK-1 serum levels were significantly lower in patients with liver cirrhosis, and that they correlated with serum markers of liver function, such as albumin, bilirubin, and platelets." (PMID 36230730, 2022). "The current meta-analysis aimed to assess the impact of albumin IV infusion on mortality and renal failure in patients with liver cirrhosis and spontaneous bacterial infection." (PMID 36721617, 2022). "Compared to those in the medium and high dose Exo-rBMMSC groups, AST and ALT expression levels in the liver cirrhosis group were markedly increased; in contrast, ALB was markedly decreased (* p < 0.05)." (PMID 36552767, 2022). "In patients with liver cirrhosis, those with regression of glucose metabolism disorders had significantly higher levels of homeostasis model assessment-β-cell function, albumin (ALB), and a significantly lower level of fibrosis-4 score." (PMID 35273920, 2022). "In patients with liver cirrhosis, due to the decline of liver cell function and the decrease in the number of liver cells, the protein synthesis including albumin and various coagulation factors is insufficient, resulting in hypoproteinemia." (PMID 35251204, 2022). "Significant differences between the healthy volunteer group with the liver cirrhosis group were found upon comparison, whereby the liver cirrhosis group had lower albumin values (p < 0.0001) and higher CRP values (0.0007)." (PMID 36553020, 2022). "In the univariate analysis, age (P = 0.020), diameter of the largest tumor (P = 0.002), liver cirrhosis (P = 0.005), serum albumin (P = 0.028), and AST (P = 0.004) were influencing factors of prognosis." (PMID 36314035, 2022). "On the contrary, sever liver cirrhosis and hypersplenism are closely correlated with a decrease in albumin and lymphocyte counts." (PMID 35846958, 2022). "Treatment with hADSC disc for 8 weeks restored normal albumin level in animals with liver cirrhosis." (PMID 36447136, 2022). "In individuals with bacterial infections and liver cirrhosis, human albumin administration can play an important role in preventing the harmful impact on renal function and circulatory function and enhancing survival." (PMID 36721617, 2022). "In this retrospective study, we investigated the predictive value of urinary albumin excretion in diabetic patients with liver cirrhosis subjected to LDLT for mortality within 3 years after surgery." (PMID 36164711, 2022). "Compared to the HBV-CLD cohort, the HBV-ACLF cohort had higher rates of liver cirrhosis, alcohol consumption, lower albumin, lower rates of family history of HCC, and higher levels of TBiL, ALT, and AST." (PMID 36339647, 2022). "Differentiating between cardiac and liver cirrhosis requires analysis of the ascitic peritoneal fluid, in particular ascitic albumin and total protein levels." (PMID 35945724, 2022). "This suggests that glucose metabolism should be evaluated in patients with liver cirrhosis after the resolution of acute liver inflammation, especially in patients with sustained low levels of ALB." (PMID 35273920, 2022).
liver cirrhosis (continued). "Several reports have shown that BCAA supplementation helps patients with liver cirrhosis recover from protein-energy malnutrition, raise serum albumin levels and subsequently improve the quality of life and survival." (PMID 33579345, 2021). "While low baseline albumin and high bilirubin values were associated with high IL6, liver cirrhosis, alcoholic liver disease, and portal vein infiltration were associated with high IL8." (PMID 34080071, 2021). "Particular focus is placed on details of the interactions between zinc and albumin and their impact on pathogenesis and therapy of liver cirrhosis." (PMID 34836265, 2021). "The levels of albumin, globulin and platelet in subjects with liver cirrhosis were lower than in the HC group." (PMID 34722597, 2021). "These three models have age and liver cirrhosis in common and other components including albumin, bilirubin, and HBV DNA levels can be easily obtained during standard patient care." (PMID 34830764, 2021). "Among them, liver cirrhosis, distant metastasis, ascites, albumin concentrations, bilirubin, AST, ALT, neutrophil, hemoglobin, and tenofovir co-treatment manifested statistically significant association with overall survival." (PMID 34829768, 2021). "The ALB (6.22 ± 3.25 × 109/L) and serum Na+ (137.22 ± 6.05 mmol/L) in liver cirrhosis patients with atrial arrhythmia were significantly lower than that in the group without atrial arrhythmia (ALB: 32.56 ± 6.91 g/L, serum Na+: 139.46 ± 4.65 mmol/L)." (PMID 34291096, 2021). "In patients with decompensated liver cirrhosis, albumin metabolism is disturbed by a range of factors." (PMID 34836265, 2021). "Patients with liver cirrhosis had lower albumin levels (p = 0.001) at baseline and SVR12, demonstrating impaired liver function in these patients." (PMID 33807462, 2021). "Studies have shown that low serum albumin is common in liver cirrhosis and is related to reduced survival rates." (PMID 34708050, 2021). "In our study, high IL6 values were associated with high total bilirubin, low albumin, and high mALBI grade; and high IL8 values were associated with liver cirrhosis, alcoholic liver disease, and portal vein invasion." (PMID 34080071, 2021). "Infusion of human albumin solution (HAS) supplements endogenous albumin in patients with cirrhosis of the liver and effectively supported antimicrobial therapy in randomized controlled trials (RCTs)." (PMID 33925831, 2021). "Low levels of albumin (HR 2.61; 95% CI 1.71–3.97, P < 0.00001) and liver cirrhosis (HR 2.91; 95% CI 1.44–5.88, P = 0.003) were significantly associated with an inferior OS." (PMID 34627251, 2021). "While clear indications of albumin exist for some patients with liver cirrhosis, large studies that demonstrate a clinically relevant advantage beyond hemodynamic effects and would therefore justify wider use in many other areas are still lacking." (PMID 34618163, 2021). "In this study, patients with liver cirrhosis showed increased levels of serum PT, AST, and GGT and decreased total protein, and albumin; of note, liver cirrhosis led to all of these changes." (PMID 33771232, 2021). "Patients with liver cirrhosis and cachexia are typically characterised by low levels of albumin, a recognised risk factor for severe CDI, and in our study, low albumin levels were strongly correlated with the risk of death." (PMID 33805755, 2021). "In conclusion, in patients with liver cirrhosis complicated by HRS, the use of terlipressin with albumin is associated with higher likelihood of HRS reversal, and decrease in serum Cr., than albumin alone." (PMID 34386597, 2021). "The patient had significant findings of liver cirrhosis with radiographic evidence of cirrhotic liver with esophageal varices and splenorenal shunt and elevated serum ascites albumin gradient." (PMID 34692357, 2021). "INBS has proposed criteria to identify liver and renal failures through liver cirrhosis, decreased albumin levels, and increased BUN and creatinine levels." (PMID 32552662, 2020).
liver cirrhosis (continued). "This study is consistent with others since tolvaptan was shown to have good efficacy in patients with liver cirrhosis, with regard to both low and high serum albumin concentrations." (PMID 33213378, 2020). "One-year survival for patients with albumin > 35, 28–35 and < 28 as stratified using Child-Pugh score for liver cirrhosis were 63%, 27% and 8% respectively." (PMID 32245389, 2020). "A chi-square test showed that the baseline data were balanced in terms of the distribution of the categorical data, including gender, albumin level, bilirubin level and the presence of liver cirrhosis (p > 0.05)." (PMID 32922536, 2020). "Overall, tolvaptan seems to have an edge while treating liver cirrhosis patients with edema since these patients often have extremely low levels of albumin and sodium in end-stage liver diseases." (PMID 32388692, 2020). "The onset of liver cirrhosis is characterized by low albumin and platelet levels and spleen enlargement." (PMID 32094392, 2020). "We previously reported the use of murine adipose tissue-derived mesenchymal stem cells to repair murine liver cirrhosis caused by NASH, demonstrating enhancement of albumin production in hepatic parenchymal cells as well as suppression of hepatic inflammation." (PMID 32229470, 2020). "We aimed to elucidate the prognostic impact of this Zn classification system in patients with liver cirrhosis (LC) compared to the Child–Pugh classification and the albumin–bilirubin (ALBI) grading system (n = 441, median age = 66 years)." (PMID 31766742, 2019). "Serum AST, ALT and bilirubin total were significantly higher in liver cirrhosis than in control group while serum albumin was significantly lower in liver cirrhosis than in control group." (PMID 30889181, 2019). "Our work included a retrospective observational study and a systematic review with meta-analysis to clarify the role of albumin infusion in prevention and treatment of overt HE in liver cirrhosis." (PMID 31596729, 2019). "A higher LMR value was significantly correlated with a high serum albumin concentration (P < 0·001), high prothrombin time (P = 0·036) and less liver cirrhosis (P = 0·008)." (PMID 31388642, 2019). "In particular, albumin, bilirubin, and PT constitute ‘Child-Pugh score,’ the indicator of both residual liver function and prognosis in the subjects with liver cirrhosis." (PMID 31615494, 2019). "We propose a novel strategy to repurpose 20% human albumin solution (HAS) as an immune-restorative drug in patients with decompensated liver cirrhosis with the aim of maintaining serum albumin at near-normal levels." (PMID 30344180, 2018). "The Child–Pugh classification, which includes ALB and PT, is useful for evaluating liver function reserve and the degree of liver cirrhosis." (PMID 29914513, 2018). "Patients with liver cirrhosis with synthetic dysfunction as evidenced by low serum albumin (<35 g/L) have lower levels of DBP, total and directly measured free S‐25(OH)D compared to patients with normal albumin." (PMID 30460340, 2018). "The ASA score, cause of liver cirrhosis, location of the tumor, TNM stage, preoperative CEA/CA19-9/AFP, albumin, total bilirubin, alkaline phosphatase, alanine aminotransferase and prothrombin time all were not significant." (PMID 27942875, 2017). "For example, miR-29c-3p showed significant positive correlations with the level of serum cholinesterase (CHE) and albumin (ALB) in liver cirrhosis patients, suggesting that the miRNA played functional roles in the establishment of liver cirrhosis." (PMID 27917899, 2016). "Especially, when there are growth of elderly, increase of GGT, decrease of albumin and increase of total bilirubin, we can measure liver cirrhosis because these are the signs of increased liver cirrhosis." (PMID 26648983, 2015).